BRIP1 (BRCA1 interacting DNA helicase 1)
Diseases named in the same sentence as BRIP1 in open-access papers (continued):
Sharing a sentence is not in itself a finding about the gene and the disease.
cancer (continued). "Regarding clinical actionability, the EXT1 variant has implications for differential diagnosis, the BRCA1 variant for therapy selection, and both the BRCA1 and the BRIP1 variants are clinically relevant for risk assessment, prevention, prophylaxis and early detection of their associated cancers." (PMID 36550207, 2023). "BRIP1 methylation is negatively correlated to its mRNA expression in many human tumors, and the expression was associated with the activation and inhabitation of several cancer-relevant pathways." (PMID 36907870, 2023). "Therefore, we used the multilevel data of human databases to analyze the expression, mutation, methylation, activation or inhabitation of cancer-related pathways, and immune characteristics of the BRIP1 gene in 33 TCGA tumors." (PMID 36907870, 2023). "Furthermore, the association of survival regarding the alteration status of BRIP1 was also analyzed in individual cancer types." (PMID 36932143, 2023). "Furthermore, our results of differential expression analysis of paired samples and the results of IHC analysis also confirmed the diagnostic role of BRIP1 in pan-cancer." (PMID 37153833, 2023). "Moreover, several cancer types mainly had BRIP1 mutations but relatively few multiple alterations, such as UCEC, SKCM, BLCA, LUAD, and CESC (8.88 vs. 0%, 5.32 vs. 0%, 3.89 vs. 1.21%, 3.0 vs. 0%, and 3.03 vs. 0%, respectively)." (PMID 36932143, 2023). "The aberrant expression of BRIP1 was associated with several cancers; however, the panoramic picture of BRIP1 in human tumors remains unclear." (PMID 36907870, 2023). "In this pan cancer analysis, the alteration of BRIP1 was 1.53% in OV, and the mutation was 1.02%." (PMID 36932143, 2023). "Of note, we found extensive associations between the expression of BRIP1 and marker genes of RNA modification, suggesting that different types of RNA modifications may regulate the expression of BRIP1 across cancers." (PMID 36907870, 2023). "Given that BRIP1 has an essential function in the regulation of normal cell cycle progression and DNA repair, the BRIP1 gene represents a good candidate for prediction of genetic susceptibility to cancer." (PMID 30800220, 2019). "For example, Due to the inconsistencies among these previous studies, we conducted this meta-analysis covering all eligible molecular epidemiology studies to validate the correlation of four most common BRIP1 polymorphisms (rs2048718, rs4988344, rs4986764, and rs6504074) and cancer risk." (PMID 29466248, 2018). "Based on the major anti–oncogenic role of the BRIP1 pathway, a low–level BRIP1 activation associated with the rs4986764C allele may lead to cancer development through an impaired DNA repair process." (PMID 28415781, 2017). "Nonsense and null mutations in BRIP1 have been implicated in various cancers." (PMID 25765652, 2015). "Moreover, a BRIP1 frameshift mutation was associated with a 36% increased risk of cancer in general and a reduced lifespan of 3.6 years compared to non-carriers." (PMID 25374583, 2014). "Truncating BRIP1 mutations have been clearly implicated as cancer susceptibility alleles." (PMID 19935797, 2009). "The BRIP1 c.104_108del (p.Gly35fs*32) variant, which results in a frameshift and subsequent loss of function, may compromise the cell’s ability to repair DNA double-strand breaks, leading to increased mutational burden and cancer risk." (PMID 39296440, 2024). "Besides, we found that BRIP1 mutation patterns were closely related to survival in several cancers." (PMID 36932143, 2023). "Second, although our work suggested that BRIP1 has the potential to be a diagnostic/prognostic biomarker for several certain cancers and could act as an effective target for immunotherapy in some tumors, further experiments in vitro/in vivo are required to verify these hypotheses." (PMID 36907870, 2023).
cancer (continued). "We suggest that the elevated BRIP1 mutation prevalence described in some studies with the focus on familial BC might be due to the co-occurrence of OC in these families, one generally used criterion to define a positive cancer family history." (PMID 29368626, 2018). "Some FA genes, such as FANCD1 [BRCA2] and FANCJ [BRIP1], act as cancer predisposition genes in a monoallelic autosomal dominant manner." (PMID 40358701, 2025). "We found a double mutation (DM) in 6 patients, with one carrying a DM in MUTYH and the other 5 harboring mutations in MUTYH and other cancer susceptibility genes (CHEK2, BRIP1, MLH1, and BRCA1)." (PMID 41001951, 2025). "Of these, 103 patients (8.6% of the total sample) carried germline pathogenic variants in genes that have been definitively linked to an increased risk of PC or other types of cancers (BRCA2, ATM, CHEK2, NBN, BRCA1, PALB2, BRIP1 and BARD1)." (PMID 41465280, 2025). "A somewhat newer entity is BRIP1, which exerts its function on a cellular level in conjunction with BRCA1 and has likewise been identified as a cancer susceptibility gene." (PMID 40988318, 2025). "Approximately 10% of patients with aggressive PC carry germline pathogenic variants in genes with established roles in cancer predisposition (BRCA2, ATM, CHEK2, NBN, BRCA1, PALB2, BRIP1, BARD1)." (PMID 41465280, 2025). "In the non‐cancer cohort, 25/492 (5%) participants carried 17 unique P/LP variants in ATM, BRCA2, BRIP1, CHEK2, MUTYH, NBN, and PMS2 genes." (PMID 38308423, 2024). "BRIP1 expression data of tumor and normal tissues were downloaded from the Cancer Genome Atlas, Genotype-Tissue Expression, and Human Protein Atlas databases." (PMID 37153833, 2023). "Our pan-cancer analysis of BRIP1 provides a valuable resource for understanding the multimolecular characteristics and biological function of BRIP1 across human cancers." (PMID 36907870, 2023). "The correlation between methylation and BRIP1 expression among different cancers was also evaluated by the GSCALite database." (PMID 36907870, 2023). "Preceding studies of BRIP1 were limited to onefold cancer type and the relatively small number of cases." (PMID 36932143, 2023). "In the current study, we also observed a high genetic alteration frequency in BRCA, and extensive SNVs of BRIP1 were found in several cancer types." (PMID 36907870, 2023). "Only 2 cases out of the 13 had heterozygous germline variants in cancer predisposition genes (RAD51D, BRIP1)." (PMID 37869077, 2023). "The current study profiled the total BRIP1 mutation spectrum and offered an extensive molecular outlook of BRIP1 in a pan cancer analysis." (PMID 36932143, 2023). "At first, we compared the mRNA expression pattern of BRIP1 between tumors and matching normal tissues among various cancer types by GEPIA2." (PMID 36932143, 2023). "In conclusion, the current study provided the first comprehensive pan cancer profile of BRIP1 abnormal expression, methylation, alteration, and their therapeutic and prognostic implications, covering 10,967 tumor samples across 32 cancer types." (PMID 36932143, 2023). "Previous studies suggested that BRIP1 has an anti-oncogenic effect and is deregulated in many cancers." (PMID 36907870, 2023). "Through pan-cancer analysis, BRIP1 emerged from a bunch of candidate genes who were applicable for broad-spectrum tumor diagnosis as it significantly upregulated in most tumors." (PMID 37153833, 2023). "Our results indicated a prognosis-related differential expression of BRIP1 between various cancers and their corresponding normal tissues." (PMID 36907870, 2023). "This study aims to explore the pan-cancerous picture of the expression of BRIP1 across 33 human cancers." (PMID 36907870, 2023). "Conclusively, our findings analyzed and summarized the potential role of BRIP1 as a promising therapeutic target in different cancer types." (PMID 36932143, 2023).
cancer (continued). "The results showed that expression, methylation, and alteration of BRIP1 varied greatly from each cancer by analyzing large comprehensive datasets with over 10,000 tumor samples." (PMID 36932143, 2023). "BRIP1 expression was also associated with the immune infiltration levels of CAFs and CD8+ T cells in specific cancers." (PMID 36907870, 2023). "We then assessed the levels of BRIP1 protein expression across different cancers in datasets from the HPA database." (PMID 36907870, 2023). "The frequency of BRIP1 alteration presented diversity in individual cancer type, with the tumor sample number varied from 36 (CHOL) to 1084 (BRCA)." (PMID 36932143, 2023). "In the current study, we performed a pan-cancer analysis of BRIP1 in various human cancers using multiple online databases to explore the impending mechanisms of BRIP1 in the carcinogenesis, development, and clinical outcomes of various human tumors." (PMID 36907870, 2023). "UCEC (9.82%), BRCA (8.39%) and BLCA (7.05%) were the cancer types ranked ahead with the higher BRIP1 alteration." (PMID 36932143, 2023). "In this study, the performance and alterations in gene expression of PALB2 and BRIP1,as well as their roles in cancer progression wasinvestigated through conductingquantitative assessments." (PMID 39430039, 2023). "PARPi activity was also demonstrated for BRCAwt cancers due to mutations in genes critical for DNA repair (e.g., ATM, BARD1, BRIP1, CHEK2, NBN, PALB2, RAD51C, and RAD51D)." (PMID 36910637, 2023). "The total BRIP1 alteration (mutation and copy number variants (CNV)) frequency was 2.21% in selective TCGA samples (242/10,967) containing 32 cancer types." (PMID 36932143, 2023). "FA displays an autosomal recessive inheritance, but cancer risk is associated with some heterozygous mutations in the following genes: BRCA2 (FANCD1), BRIP1 (FANCJ), PALB2 (FANCN), RAD51C (FANCO), BRCA1 (FANCS)." (PMID 37239385, 2023). "To further figure out the role of BRIP1 in tumors, we used various databases to explore the prognostic potential of BRIP1 in various cancers according to gene expression." (PMID 36907870, 2023). "Since this is the region where BRIP1 locates and with our finding of BRIP1 amplification and its role in pan-cancer, the phenomenon shall be explained to some extent." (PMID 37153833, 2023). "We observed prognosis-related differential BRIP1 expressions between various carcinomas and the corresponding normal tissues." (PMID 36907870, 2023). "For each patient, we also showed the risk in the well-known high-penetrance cancer risk alleles BRCA1 and BRCA2 with respect to other moderate-penetrance alleles including PALB2, CHEK2, ATM, BARD1, RAD51D, RAD51C and BRIP1." (PMID 35886069, 2022). "PV were detected in 13 cancer predisposition genes including ATM (n=4), BLM (n=1), BRCA1 (n=1), BRCA2 (n=7), BRIP1 (n=1), CDKN2A (n=1), CHEK2 (n=9), FANCC (n=1), MUTYH (n=10), NBN (n=1), PALB2 (n=1), RAD51D (n=1) and STK11 (n=1)." (PMID 36091166, 2022). "Other highly mutated HR-related genes, including RAD51B (mutation frequency in patients, 6.1%), ATR (6.1%), ATM (6.1%), PALB2 (6.1%), and BRIP1 (4.9%), have been reported to be capable of affecting the sensitivity of various cancer cells to PARPis." (PMID 35952757, 2022). "Pathogenic variants in BRCA2/FANCD1, PALB2/FANCN, BRIP1/FANCJ, and RAD51C/FANCO have known adult-onset cancer risks, and there are recommendations for carriers to have increased cancer surveillance, consider chemoprevention, or undergo preventative surgeries." (PMID 35359366, 2022). "Amongst these, ‘breast cancer 1, early onset (BRCA1)’; ‘BRCA1 associated RING domain 1 (BARD1)’; ‘BRCA1 interacting protein C-terminal helicase 1 (BRIP1)’; ‘H2A histone family, member X (H2AFX)’ and RAD51." (PMID 33491125, 2021).
cancer (continued). "Several cancer-associated genes have been identified on chromosome 17q, including PPM1D, EME1, BRCA1, ERBB2, NF1, RAD51C, BRIP1 and BIRC5." (PMID 34885154, 2021). "The global importance of such rare variants in tumorigenesis has been addressed by pan-cancer analysis, revealing significant enrichments for protein truncating variants in genes such as ATM, BRCA1/2, BRIP1, and MSH6." (PMID 33809641, 2021). "Since loss-of-function variants in the BRIP1 and PALB2 genes increase the risk of BC and OC28,29, these variants were considered to be the main cause of the increased cancer risk in these two families." (PMID 34282249, 2021). "Consistent with the results from the cancer cell lines, targeting BRIP1 as well as several other components of the FA pathway, such as FANCD2 and FANCI, significantly impaired the fitness of ALDH2 KO cells as compared to the WT." (PMID 34454516, 2021). "Both variants are reported with low frequency in the gnomAD non-cancer population (MAF < 0.00002) and the BRIP1 variant has been described as pathogenic in ClinVar." (PMID 33840814, 2021). "Based on the PARIS prediction, cancer cell lines that express low levels of ALDH2 become dependent on BRIP1, possibly to balance a harmful increase in genomic instability." (PMID 34454516, 2021). "Relative to BRCA1 and BRCA2, less is known of the role of BRIP1 and CHEK2 cancer predisposing genes in conferring risk of BC and OC in FCs." (PMID 34298626, 2021). "Remarkably, the present work also demonstrated that higher expression of UBE2T, RFC4, POLQ, BRIP1, and H2AFX is especially associated with worse overall survival (HR > 5) in several types of cancer (Group A and D)." (PMID 34853396, 2021). "Specifically, we propose that our results represent the basis for future investigations of the role of BRIP1 as a potential cancer therapeutic target in an in vivo setting." (PMID 34454516, 2021). "To understand how ALDH2 and BRIP1 levels are regulated in human tumors, we looked at cancer gene expression data obtained from the TCGA and compared them to those found in the normal tissue controls derived from the Genotype-Tissue Expression (GTEx) database." (PMID 34454516, 2021). "Family members of patients with FA who are heterozygous carriers of PV in genes from the fourth module FANCD1 (BRCA2), FANCJ (BRIP1), FANCN (PALB2), FANCO (RAD51C) and FANCS (BRCA1) are at increased risk to develop cancer." (PMID 33371494, 2020). "BRIP1 plays major role in DNA repair, type J Fanconi anemia, development of various cancers, including BC." (PMID 32888398, 2020). "Only the POLE p.Y1078fs (AC/AN = 1/17,692, AF = 0.0056%) and BRIP1 p.E1222fs (AC/AN = 11/19,232, AF = 0.057%) were present exclusively in the East Asian ancestry of gnomAD-non-cancer dataset." (PMID 32471518, 2020). "In this network, four FA-gene products (FANCD1/J/N/S) are previously well-known DNA damage repair proteins (respectively for BRCA1/2, BRIP1 and PALB2), conferring human cancer susceptibility in breast, ovary, prostate, and/or others." (PMID 33099537, 2020). "This meta-analysis based on 18 studies involving 13,716 cancer patients and 15,590 cancer-free controls is aimed at to evaluate the relationship between the four common SNPs of BRIP1 (rs2048718, rs4988344, rs4986764, and rs6504074) and cancer risk." (PMID 29466248, 2018).
cancer (continued). "Previous studies have reported that overexpression of BRIP1 promotes the migration and invasion of cancer cells, while knockdown of BRIP1 suppresses this process." (PMID 30240439, 2018). "The association of ‘early’ FA genes with FANCD2 monoubiquitination defects with increased cancer susceptibility is much weaker compared with the ‘late’ FA genes such as BRCA1, BRCA2, BRIP1, PALB2 and RAD51C." (PMID 26085575, 2015). "The spectrum of cancers in the BRIP1-positive families was wider than that of RAD51C&D." (PMID 40282418, 2025). "Each case carried VUS in genes related to DNA repair (POLD1, BARD1, or BRIP1); however, given the uncertain classification of these variants, no direct inference regarding hereditary cancer predisposition can be made." (PMID 41595443, 2025). "Other homologous recombination DNA damage repair (HR-DDR) genes associated with other cancer risks besides breast and ovarian, such as ATM (n = 9), BARD1 (n = 4), BRIP1 (n = 2), CHEK2 (n = 5), PALB2 (n = 5), RAD51C (n = 1), and RAD51D (n = 7), accounted for an additional 4% (33/769)." (PMID 40065011, 2025). "While most heterozygous carriers do not appear to have significantly increased cancer risks, susceptibility to cancer, including CRC, is well established for carriers of heterozygous pathogenic variants in FANCS/BRCA1, FANCD1/BRCA2, FANCN/PALB2, FANCJ/BRIP1, and FANCO/RAD51C." (PMID 41155398, 2025). "PTVs in BRIP1 have been associated with ovarian cancer; the carrier in our cohort had no additional primary cancer diagnoses (49 years)." (PMID 39315505, 2025). "Additionally, a literature search regarding the pathophysiology of BRIP1-mutations and the role of PARP-inhibitors in BRIP1-mutated cancer was conducted." (PMID 40988318, 2025). "BRIP1 protein was mostly studied in breast and ovarian cancer." (PMID 39767562, 2024). "Similarly, the discovery of novel variants in BRIP1 and MLH1 underscores the importance of DNA repair mechanisms in maintaining genomic integrity and preventing cancer." (PMID 39296440, 2024). "Controversially, data from ONCOMINE, TIMER2, and HPA databases suggested that BRIP1 is highly expressed in most cancers, and results from GEPIA2 suggested that gene expression is associated with cancer stages, indicating that BRIP1 plays an oncogene role in human tumors." (PMID 36907870, 2023). "Pathways of “basal transcription factors,” “homologous recombination,” and “nucleotide excision repair” might partially explain the role of BRIP1 on tumorigenesis of different cancers." (PMID 36907870, 2023). "In this section, we used the ciBioportal to explore BRIP1 CNVs in different cancer." (PMID 36932143, 2023). "Although BRIP1 seemed to be a novel biomarker of vital clinical utility in predicting diagnosis and prognosis in pan-cancer, the distinct effects of the differential expression of BRIP1 on protein function in various cancer types remain largely unknown." (PMID 37153833, 2023). "Besides, we found a significant differential expression between tumor stage I, II and stage III, IV in ACC, KIRP, LUAD, and OV, suggesting the predicting role of BRIP1 in early diagnosis of these cancers is worth looking forward to." (PMID 37153833, 2023). "In the current work, we investigated BRIP1 expression in pan cancer." (PMID 36932143, 2023). "Additionally, the correlation between BRIP1 expression and cancers with different pathological stages was investigated using the “Pathological Stage Plot” module of GEPIA2." (PMID 36907870, 2023). "BRIP1 alterations and expression were correlated with patient prognosis in some cancer types." (PMID 36932143, 2023). "Although a small number of studies had focused on BRIP1, an extensive study of BRIP1 genetic mutation and its clinical application in different cancer types had not been analyzed." (PMID 36932143, 2023). "The abnormal expression of BRIP1 was detected in varieties of cancer types." (PMID 36932143, 2023).